RN7SL812P (RNA, 7SL, cytoplasmic 812, pseudogene)
Gene: Miscellaneous RNA gene on chromosome 22 (20,481,935 to 20,482,213, reverse strand). Ensembl gene ENSG00000242876.
Homologues: Orthologues: chimpanzee Metazoa_SRP (95% identical), macaque Metazoa_SRP (78% identical). Paralogues in human: RN7SL1 (80% identical), RN7SL2 (79% identical), RN7SL3 (77% identical), RN7SL478P (76% identical), RN7SL296P (76% identical), RN7SL14P (76% identical), RN7SL788P (76% identical), Metazoa_SRP (75% identical), RN7SL126P (75% identical), RN7SL357P (75% identical), RN7SL581P (75% identical), RN7SL711P (75% identical), and 703 more.